HSPB8 (heat shock protein family B (small) member 8)
Diseases named in the same sentence as HSPB8 in open-access papers (continued):
Sharing a sentence is not in itself a finding about the gene and the disease.
neuropathy (13 papers, 2011 to 2025). A disorder affecting the nervous system that manifests with pain, tingling, numbness, and/or muscle weakness. "Noteworthy, mutations in BAG3, the obligatory partner of HSPB8, cause cardiomyopathy, besides neuropathy and myopathy, and mutations in other HSPBs (HSPB5, HSPB6, and HSPB7) also associate with cardiac pathology." (PMID 40467930, 2025). "Our study underlines the importance of HSPB8 genetic testing in neuropathy and (cardio)myopathy in undiagnosed patients, even in the absence of clear autosomal dominant inheritance pattern in a family." (PMID 40467930, 2025). "Overall, this rescue of motor defects accompanied by the restoration of mitochondrial activity and mitophagy suggested that mitochondrial dysfunction has a critical role in the pathogenesis of HSPB8 mutation-induced neuropathies." (PMID 36979812, 2023). "HSPB8 K141 mutations have been mainly described in patients suffering from neuropathy, but myopathy with neurogenic involvement has been also linked to K141E mutation." (PMID 35281256, 2022). "Patients with HSPB8 mutations present with a very similar phenotype as patients with HSPB1-linked neuropathy, with the exception that thigh weakness, CNS involvement, and autosomal recessive transmission have not been observed." (PMID 32323160, 2020). "Whereas a muscle-specific pathomechanism can be envisioned for the frameshift mutations, the myopathy phenotype caused by HSPB8 p.K141E, which is typically associated with neuropathy, is more intriguing." (PMID 32093037, 2020). "In humans, mutations in the gene encoding Hspb8 can lead to the development of various diseases such as myopathies and neuropathies." (PMID 32604890, 2020). "In the human HSPB8, this residue corresponds to lysine 141 (K141) when mutated leads to pathological states such as neuropathy." (PMID 30032358, 2018). "In conclusion, we generated Drosophila models of HSPB8-associated neuropathies." (PMID 36979812, 2023). "In this study, we explore the evolutionary history of four human sHSPs: HspB1, HspB3, HspB5, and HspB8, all known disease factors as mutant alleles have been found associated with various forms of neuropathies, myopathies, and with cataracts in the lens of the eye." (PMID 35678958, 2022). "The changes we find in the inter-link patterns between FUSm and HspB8-WT or the neuropathy-causing mutant HspB8-K141E may appear counter-intuitive at first sight as far as they suggest a higher binding affinity of the mutant for FUS than the HspB8-WT." (PMID 34487489, 2021). "We then assessed whether Drosophila Hsp67Bc variants could mimic defects observed in patients with neuropathies and due to HSPB8 hot-spot mutations (K141E/N)." (PMID 30032358, 2018). "Our studies suggest the importance of HSPB8 genetic testing not only for neuropathy and myopathy but also for cardiomyopathy." (PMID 40467930, 2025). "So far, little is known about the influence of neuropathy-linked mutations in HSPB1 and HSPB8 on the formation and dynamism of stress granules." (PMID 32323160, 2020). "In this study, we modeled HSPB8 mutant-induced neuropathies in Drosophila." (PMID 36979812, 2023). "Moreover, mutations in HSPB8 and BAG3 have been reported to be associated with neuropathy and myopathy." (PMID 33168630, 2021). "Similarly, HSPB1 or HSPB8 have been described in neuropathies and/or myopathies." (PMID 35281256, 2022). "Apart from the typical pure neuropathy phenotype, HSPB8 mutations may cause myopathy, with or without neurogenic involvement." (PMID 32093037, 2020). "However, a recent report describes several patients with an HSPB8 frameshift mutation leading to haploinsufficiency associated with a late (adult) onset myopathy but not with neuropathy." (PMID 28780615, 2018).
cardiomyopathy (12 papers, 2009 to 2025). A disease of the heart muscle or myocardium proper. "The family history revealed a familial inheritance of the HSPB8 variant, with his mother exhibiting similar, but milder, phenotypes and his maternal uncle developing myopathy and passing away from cardiomyopathy in his 50s." (PMID 40467930, 2025). "One study showed that single point mutations in the HSPB8 gene, which encodes for HSP22, such as K141N, can cause cardiomyopathy." (PMID 35011676, 2021). "Our findings with shRNA mediated knockdown on HspB8 demonstrated that the benefits of enhancing the autophagy-lysosome-pathway on R120G-induced cardiomyopathy were lost with loss-of-function of HspB8." (PMID 32581848, 2020). "Although cardiomyopathy has been reported only in a family, considering that HSPB8 is expressed in cardiac muscle and that cardiomyopathy occurs in a mouse model of HSPB8 disease, screening for underlying cardiac involvement should be part of patient care." (PMID 40243504, 2025). "HspB8 (Hsp22) also plays a critical role in cardiac homeostasis as mice with germline ablation of HspB8 develop worse cardiomyopathy and increased mortality as compared with wild-type controls in response to pressure overload." (PMID 32581848, 2020). "In cultured cells, HSPB1 and HSPB8 overexpression prevented the aggregation of R120G and cardiac-specific HSPB8 overexpression prevented the aggregation and the cardiomyopathy progression in R120G transgenic mice." (PMID 25961584, 2015). "To clarify the functional role of HSPB8 induction on the development of HSPB5 R120G cardiomyopathy and test sufficiency, we generated a TG mouse, in which HSPB8 is overexpressed in a cardiac-specific manner using the inducible α-myosin heavy chain promoter." (PMID 19399179, 2009). "So far, only a few patients with HSPB8 variants showed respiratory insufficiency, and none of them had cardiomyopathy, which we found in our patients I and II, and the uncle of patient III." (PMID 40467930, 2025). "Although cardiomyopathy might be unrelated to HSPB8, this chance is small, as WES analysis excluded relevant variants in cardiomyopathy-associated genes." (PMID 40467930, 2025). "However, TG mice overexpressing HSPB8 K141N in cardiac tissue show aggregating HSPB8 and mitochondrial dysfunction in cardiomyocytes and develop signs of cardiomyopathy at the age of 6 months, while KO mice show cardiac defects with aging." (PMID 35281256, 2022). "HSPB8 is a heat shock protein and is also involved in cardiac development and cardiomyopathy." (PMID 34859074, 2021). "Indeed, preventing aggregate formation has been suggested as the mode by which HSPB8 can prevents desmin-related cardiomyopathy." (PMID 21731611, 2011). "Cardiac-specific TG mice expressing HSPB8 also inhibit the progression of cardiomyopathy in the R120G TG mice, suggesting that the induction of HSPB8 may play a role in inhibiting the development of DRM." (PMID 19399179, 2009). "Interestingly, HSPB8 mutations have not been correlated with cardiomyopathies, unlike BAG3 substitutions." (PMID 35281256, 2022). "Fourth, studies have shown that recombinant HSPB8 or HSPB1 can interrupt amyloid formation, thus proving to be a potential therapeutic strategy for treating certain cardiomyopathies." (PMID 35011676, 2021). "Analogously, we have demonstrated that TFEB-induced upregulation of HspB8, a BAG3 partner, was essential for chaperoning desmin back to its physiologic localization state in a mouse model of R120G αB-crystallin induced cardiomyopathy." (PMID 32581848, 2020). "In the model tested here, we found that long-term treatment with GGA results in HSPB8 induction and a similar level of overexpression of HSPB8 via transgenic manipulation recapitulates the protective effect of GGA in HSPB5 R120G cardiomyopathy." (PMID 19399179, 2009).
cardiomyopathy (continued). "Notably, mice studies correlated HSPB8 with cardiac functionality: transgenic mice overexpressing mutant HSPB8 in cardiac tissue exhibited mild cardiomyopathy, while no obvious phenotype was observed in an HSPB8 knock-out mouse." (PMID 40467930, 2025).
heart failure (10 papers, 2015 to 2023). Inability of the heart to pump blood at an adequate rate to meet tissue metabolic requirements. "Although that Hspb8 KO had a normal behaviour and physiology, they showed an increased susceptibility to heart failure under the specific context of cardiac overload." (PMID 28780615, 2018). "In a mouse heart failure model, increased HSPB8 expression stimulates mitochondrial oxidative phosphorylation, whereas its deletion has the opposite effect." (PMID 36979812, 2023). "Therefore, the function of HSPB8 seems two-edged in heart diseases: HSPB8 reveals beneficial effects on myocardial ischemia by conserving the mitochondrial function and energy production, and HSPB8 is a mediator of cardiac hypertrophy and thereby results in heart failure." (PMID 28484965, 2017). "Overexpression of HSPB8 promotes cardiomyocyte survival after ischemia in mice and attenuates the myocardial damage and contractile dysfunction in pig, whereas depletion of HSPB8 in mice with pressure overload contributes to the cardiac dysfunction and accelerates transition to heart failure." (PMID 28484965, 2017). "Notably, the stress-responsiveness of CASA at this early stage in heart failure progression was intact as suggested by significant increases in HSP70, HSPB8, and CHIP at the myofilament." (PMID 34011988, 2021). "Similarly, treatment of the CryABR120G mutant mouse model of desmin-related cardiomyopathy with the drug geranylgeranyl-acetone (increasing HSPB8 and HSPB1) significantly reduces heart failure." (PMID 26664897, 2015).
amyotrophic lateral sclerosis (8 papers, 2012 to 2025). Amyotrophic lateral sclerosis (ALS) is a neurodegenerative disease characterized by progressive muscular paralysis reflecting degeneration of motor neurons in the primary motor cortex, corticospinal tracts, brainstem and spinal cord. "For example, compensatory mechanisms or other pathogenic amyotrophic lateral sclerosis mechanisms might neutralize the expected benefits of HSPB8 upregulation or autophagy enhancement in patients." (PMID 39291166, 2024). "Alterations in the Hsp70/BAG3/HspB8 complex have been implicated in the accumulation of misfolded proteins and emergence of motor neuron diseases such as amyotrophic lateral sclerosis (ALS) and distal motor neuropathy." (PMID 31209204, 2019). "In neurons, HSPB8 has been demonstrated to protect against neurotoxicity in several models of neurodegenerative diseases, such as amyotrophic lateral sclerosis and fronto-lateral temporal dementia, by facilitating autophagy." (PMID 40725218, 2025). "HSPB8 functions as a chaperone interacting with the Bcl-2 associated athanogene 3 (BAG3) during autophagy and promotes the removal of misfolded proteins involved in amyotrophic lateral sclerosis (ALS) and other motor neuron diseases, such as TDP-43." (PMID 40385290, 2025). "HSPB8 was also shown to promote autophagic removal of misfolded proteins involved in amyotrophic lateral sclerosis (ALS)." (PMID 25051369, 2014). "Here, we demonstrated that HSPB8 also counteracts accumulation of aberrantly localized misfolded forms of TDP-43 and its 25 KDa fragment involved in most sporadic cases of Amyotrophic Lateral Sclerosis (sALS) and of Fronto Lateral Temporal Dementia (FLTD)." (PMID 26961006, 2016).
cardiac hypertrophy (8 papers, 2009 to 2023). "HSPB8-transgenic mice bearing the K141N mutation expressed myocardial hypertrophy, ventricular dysfunction, and apical fibrosis—the latter being a hallmark of heart involvement in CCC." (PMID 25210230, 2014). "The levels of aggregates as well as cardiac hypertrophy were similar between the tTA/HSPB8/R120G triple TG mice treated with doxycycline and the HSPB5 R120G TG mice." (PMID 19399179, 2009). "Moreover, HspB8 ensures the proteolytic degradation of misfolded proteins such as in the case of the HspB8 mediated‐cardiac hypertrophy." (PMID 37243950, 2023). "Furthermore, HSPB8 is a small heat shock protein whose heart specific overexpression induces myocardial hypertrophy." (PMID 25210230, 2014).
ovarian carcinoma (8 papers, 2017 to 2025). A malignant neoplasm originating from the surface ovarian epithelium. "In ovarian cancer cell lines, the downregulation of HSPB8 positively directs the migration progress of the transforming growth factor alpha (TGF-α) for ovarian cancer cells." (PMID 34235216, 2021). "To identify the involvement of small HSPs (HSPB5, HSPB6, and HSPB8) in OvCa during the development of chemoresistance, we used OvCa cell lines: A2780 and SKOV3, which represents distinct types of ovarian cancer cell lines." (PMID 34177409, 2021).
gastric cancer (7 papers, 2020 to 2025). A primary or metastatic malignant neoplasm involving the stomach. "HSPB8 promotes cancer cell growth and is associated with poor prognosis in patients with gastric cancer." (PMID 31967976, 2020). "In gastric cancer, the evaluation of the expression levels of HSPB8 may help to identify high-risk gastric cancer patients and thus aid the selection of appropriate therapies." (PMID 33562660, 2021). "This study presents a compelling shift in our understanding of the molecular intricacies underlying gastric cancer development, shedding light on the multifaceted roles of EEF1A2 and HSPB8 in this context." (PMID 38172654, 2024). "HSPB8 is detected to be overexpressed in gastric cancer, and it regulates the proliferation and apoptosis progress of gastric cells by activating the ERK-CREB signaling." (PMID 34235216, 2021). "Notably, EEF1A2 appears to function as an oncogene in the progression of gastric cancer, exerting its influence through the promotion of HSPB8." (PMID 38172654, 2024).
prostate carcinoma (7 papers, 2012 to 2025). A carcinoma that arises from epithelial cells of the prostate gland. "All such results supported a strong association between HSPB8 expression and the severity of prostate cancer, with lower HSPB8 expression generally observed among patients exhibiting more pronounced abnormalities in prostate cancer-related parameters." (PMID 41190325, 2025). "In this study we identified HSPB8 as new biomarker with potential diagnostic, therapeutic and prognostic values in prostate cancer through WGCNA." (PMID 41190325, 2025). "Since PI3K−AKT signaling was identified as the third most enriched KEGG pathway in gene enrichment analysis, we speculated that it might be linked to HSPB8’s tumor-suppressive role in prostate cancer." (PMID 41190325, 2025). "It is still unclear whether the same pathways are used by the restored H11/HspB8 to cause cell death in prostate cancer, Ewing sarcoma, and/or hematologic malignancies." (PMID 23056924, 2012). "Our mechanistic studies revealed that HSPB8 knockdown promoted phosphorylation of AKT and mTOR, which aligned with our speculation, i.e., the inhibitory role of HSPB8 in prostate cancer was, at least in part, linked to the inactivation of PI3K−AKT signaling pathway." (PMID 41190325, 2025). "HSPBP1 expression was significantly higher in prostate cancer groups than in normal controls, while HSPA13 and HSPB8 showed lower expression levels among prostate cancer tissues." (PMID 41190325, 2025). "After siHSPB8 transfection two prostate cancer cell lines showed significantly reduced HSPB8 expression levels." (PMID 41190325, 2025). "As expected, HSPB8 knockdown substantially increased proliferative rates of two prostate cancer cell lines DU145 and 22Rv1." (PMID 41190325, 2025). "This is in line with existing data and indicates that HSPB8 functions as a tumor suppressor gene during the initiation and progression of prostate cancer." (PMID 41190325, 2025). "In aggregate, this study provided a novel insight into the pathogenesis of prostate cancer and targeting HSPB8 appeared to be an emerging area in prostate cancer treatment." (PMID 41190325, 2025). "On the molecular and cellular levels, HSPB8 silencing induced cellular proliferation and enhanced invasive and migratory capacities of prostate cancer cell lines." (PMID 41190325, 2025). "Our data demonstrated that HSPB8 exhibited lower expression levels in prostate cancer tissues than in normal prostatic tissues." (PMID 41190325, 2025). "By employing the ESTIMATE algorism, we investigated the association of HSPB8 with stromal and immune components in TIME based on obtained stromal score, immune score and ESTIMATE score of prostate cancer samples." (PMID 41190325, 2025). "HSPB8 is also found to be epigenetically silenced in human prostate cancer, Ewing’s sarcoma cells and in hematological malignancies." (PMID 33133131, 2020). "H11/HspB8 is similarly silenced in prostate cancer and Ewing's sarcoma cells and in hematologic malignancies." (PMID 23056924, 2012). "Overall, this study offers a new understanding into the pathogenesis of prostate cancer, proposing that targeting HSPB8 might be a promising area in prostate cancer treatment." (PMID 41190325, 2025). "As a tumor suppressor gene, lack of HSPB8 was associated with unfavorable survival outcomes among patients with prostate cancer." (PMID 41190325, 2025). "Using multiple bioinformatic and experimental methods, we studied HSPB8’s biological functions, explored the relationship between HSPB8 and patients’ survival, and investigated HSPB8’s impacts on TIME of prostate cancer." (PMID 41190325, 2025). "First, we employed the downloaded gene matrix to compare the expression of HSPB8, HSPBP1 and HSPA13 levels between normal and prostate cancer samples for validation purposes." (PMID 41190325, 2025).
prostate carcinoma (continued). "In this study we screened out HSPB8 as a potential biomarker from the HSP family using bioinformatic methods, and further investigated its biological role as well as its prognostic significance in prostate cancer." (PMID 41190325, 2025). "However, pan-cancer data from GEPIA showed significant differences in terms of HSPB8 expression between normal prostatic tissues and prostate cancer samples while this was not the case for HSPBP1 and HSPA13." (PMID 41190325, 2025).